MASTL (microtubule associated serine/threonine kinase like)
Diseases named in the same sentence as MASTL in open-access papers (continued):
Sharing a sentence is not in itself a finding about the gene and the disease.
breast carcinoma (continued). "Sensitive cancer cells require MASTL kinase activity and expression of the B55 subunits of PP2A, suggesting the presence of a subgroup of breast cancer patients that could benefit from MASTL-directed therapies." (PMID 29229993, 2018). "Furthermore, MASTL depletion increased the radiosensitivity of breast cancer cells and reduced the formation of the radioresistant breast cancer stem cells." (PMID 29976159, 2018). "All together, these data suggest that the PP2A inhibitory kinase MASTL may have both prognostic and therapeutic value in human breast cancer." (PMID 29229993, 2018). "In addition, MASTL inhibition enhanced the radiosensitivityof breast cancer cells through a reduction in the formation of cancer stemness." (PMID 29976159, 2018). "Furthermore, MASTL depletion enhanced the radiosensitivity of breast cancer cells with increased PP2A activity." (PMID 29976159, 2018). "Notably, MASTL depletion dramatically reduced the formation of radioresistant breast cancer stem cells in response to irradiation." (PMID 29976159, 2018). "Next, we analysed MASTL protein and mRNA expression in a panel of 20 breast cancer cell lines." (PMID 29743597, 2018). "Notably, our data showed that MASTL inhibition-mediated mitotic cell death enhanced the radiosensitivity of breast cancer cells through a reduction in the formation of cancer stem cells and that MASTL inhibition increased DNA damage." (PMID 29976159, 2018). "Therefore, our data suggested that MASTL inhibition was able to induce mitotic cell death through PP2A activation in breast cancer cells." (PMID 29976159, 2018). "Importantly, both MASTL mRNA and protein were overexpressed in breast cancer cells (red) compared with primary human mammary epithelial (HMEC, 184) and immortalised non-tumorigenic MCF10A and 12 A cells (blue)." (PMID 29743597, 2018). "Importantly, knockdown of MASTL, reduced cell proliferation, prevented invasion and metastasis of MDA-MB-231 breast cancer cells both in vitro and in vivo, indicating the potential of future therapies that target MASTL." (PMID 29743597, 2018). "Thus, our results suggested that MKI-1 inhibited MASTL in breast cancer cells." (PMID 33117702, 2020). "Therefore, to better understand how MASTL overexpression could be driving breast cancer, we undertook an unbiased phosphoproteomic screen using stable isotope labelling of amino acids in cell culture (SILAC)." (PMID 29743597, 2018). "Besides the relevance of MASTL as a potential new therapeutic target for breast cancer, our data suggest it may also have prognostic value in breast tumors." (PMID 29229993, 2018). "On the other hand, it has been demonstrated that MASTL is involved in cell spreading and attachment to the ECM in mammary epithelial and breast cancer cells in a kinase-activity independent manner." (PMID 38533088, 2024). "Conversely, ablation of MASTL expression impaired the proliferation and metastasis of MDA-MB-231 breast cancer cells in vitro and in vivo." (PMID 36247015, 2022). "In the current study, our data reported the second-generation MASTL inhibitor MKI-2, a new potent MASTL inhibitor with in vitro IC50 of 37.44 nM and cellular IC50 of 142.7 nM in breast cancer cells." (PMID 34358073, 2021). "Our data showed that MKI-2 inhibited recombinant MASTL activity and cellular MASTL activity with IC50 values of 37.44 nM and 142.7 nM, respectively, in breast cancer cells." (PMID 34358073, 2021). "Our previous report also showed that MKI-1 inhibited MASTL with in vitro IC50 of 9.9 μM and reduced phosphorylated ENSA with the induction of aberrant nuclear cells in breast cancer cells." (PMID 34358073, 2021). "Our results have demonstrated a new small-molecule inhibitor of MASTL, MKI-1, which exerts antitumor and radiosensitizer activities through PP2A activation in breast cancer in vitro and in vivo." (PMID 33117702, 2020).
breast carcinoma (continued). "The ability of MASTL knockdown to delay both primary tumour growth and prevent metastasis suggests that inhibiting MASTL may be a valid therapeutic strategy for the treatment of breast cancer, which is also supported by another manuscript that was published during the revision of our paper." (PMID 29743597, 2018). "To validate that MKI-2 inhibited MASTL in breast cancer cells, we first examined whether MKI-2 inhibits phospho-ENSA in three breast cancer cell lines, including MCF7, BT549, and MDA-MB468 cells." (PMID 34358073, 2021). "In our study, we showed that PP2A-B55α, a key downstream target of MASTL, reduced c-Myc phosphorylation and protein level, suggesting that c-Myc may be regulated by PP2A-B55 in breast cancer cells." (PMID 33117702, 2020). "As MASTL inhibits PP2A activity in various models, including cancer cells, we examined whether MKI-1 regulated PP2A activity in breast cancer cells." (PMID 33117702, 2020). "Therefore, it is likely that MASTL inhibitors, such as MKI-1, are useful drugs for both anticancer treatment and as a potential radiosensitizer in breast cancer." (PMID 33117702, 2020). "Therefore, our study provides evidence that MKI-1 is a new inhibitor of MASTL with antitumor and radiosensitizer activities resulting from PP2A activation in breast cancer." (PMID 33117702, 2020). "The depletion of MASTL reduced the oncogenic properties of breast cancer cells with high MASTL expression, but did not affect the viability of non-transformed normal cells with low MASTL expression." (PMID 29976159, 2018). "MASTL depletion reduced the oncogenic properties through the selective induction of mitotic catastrophe in breast cancer cells and not in non-transformed normal cells." (PMID 29976159, 2018). "We found that mammosphere formation was reduced in the MASTL-depleted MCF7 and T47D cells in response to irradiation, which suggested that MASTL inhibition was able to reduce breast cancer stemness in response to irradiation." (PMID 29976159, 2018). "Our data suggested that MASTL inhibition promoted mitotic catastrophe through PP2A activation, which led to the inhibition of cancer cell growth and a reversal of radioresistance in breast cancer cells." (PMID 29976159, 2018). "Our data showed that MASTL inhibition induced mitotic catastrophe through PP2A activation; in turn, this preferentially inhibited cancer growth and enhanced the radiosensitivity of breast cancer cells." (PMID 29976159, 2018). "In addition, we examined whether MKI-2 increases PP2A activity and inhibits c-Myc since we previously observed that MASTL inhibition activates PP2A and decreases c-Myc stability in breast cancer cells." (PMID 34358073, 2021). "To confirm that MKI-1 inhibited MASTL in breast cancer cells, we first determined whether MKI-1 inhibited the phosphorylation of ENSA in two breast cancer cell lines, MCF7 and T47D, which cells expresses high MASTL." (PMID 33117702, 2020). "Taken together, these results suggest that high MASTL expression correlates with increased proliferation, tumour grade and CIN, and may be an independent prognostic factor for metastasis-free survival in breast cancer." (PMID 29743597, 2018). "Taken together, these results suggest that MASTL overexpression correlates with deregulation of desmosomes, actin regulatory proteins, disruption to PI3K/AKT/mTOR signalling and an increase in DNA damage signalling across patient tumour samples, breast cancer cell lines and our MCF10A model system." (PMID 29743597, 2018). "While the MASTL transcription factor is currently unknown, MASTL is a potential DREAM target and recent evidence also suggests that MASTL transcription can be increased by E2F8 in ER positive breast cancer cells." (PMID 30555827, 2018). "Therefore, our results suggested that MASTL inhibition selectively reduced the oncogenic properties of breast cancer cells and did not affect the viability of normal cells." (PMID 29976159, 2018).
colon cancer (6 papers, 2018 to 2023). "MASTL(microtubule associated serine/threonine kinase-like)promotes the progression and chemo-resistance of colon cancer by activating the WNT/β-catenin signaling pathway." (PMID 37914721, 2023). "The data presented in this study strongly supports a promotive role for MASTL in colon cancer, and the potential association of MASTL with anti-cancer therapy efficacy." (PMID 30068336, 2018). "However, a causal association of MASTL in regulating colon cancer growth and progression and its potential role in resistance to conventional therapy, a critical factor in unrelenting patient death, remains an area of active investigation." (PMID 30068336, 2018). "Taken together, our data identify a novel PYCR2/MASTL/Wnt/β-catenin signaling pathway that promotes colon cancer." (PMID 37508547, 2023). "We further demonstrated that MASTL overexpression promotes colon cancer aggressiveness by promoting cancer stem cells, similar to PYCR2." (PMID 37508547, 2023). "Our studies also supported the observation that MASTL induces Wnt/β‐catenin signaling in colon cancer by regulating glycogen synthase kinase‐3 beta (GSK3β) phosphorylation." (PMID 32692487, 2020). "MASTL overexpression promotes cell transformation in breast and colon cancer cells through hyperphosphorylation of the oncogenic kinase AKT or Wnt/β‐catenin signaling." (PMID 32692487, 2020). "Another report showed that MASTL inhibition reduced c-Myc and its target genes, such as survivin and Bcl-xl, in colon cancer cells." (PMID 33117702, 2020). "MASTL is known to regulate cell proliferation, tumor growth, and metastasis in vivo in breast, thyroid, and colon cancer cells." (PMID 32692487, 2020). "The present study depicts a novel role for MASTL in regulating Wnt/β-catenin signaling to modulate c-Myc and Survivin expression in promoting colon cancer and therapy resistance." (PMID 30068336, 2018). "Further, inhibition of MASTL expression arrested cell cycle progression in colon cancer cells at the G2/M interphase, and induced apoptosis." (PMID 30068336, 2018). "Our findings suggest that MASTL overexpression can contribute to anti-cancer drug resistance in colon cancer cells by up-regulating Survivin and Bcl-xL expressions." (PMID 30068336, 2018). "In contrast, forced overexpression of full-length MASTL cDNA in colon cancer cells induced sharp increases in the expression of these proteins." (PMID 30068336, 2018). "Further, the shRNA silencing of MASTL expression in colon cancer cells induced cell cycle arrest and apoptosis in vitro and inhibited xenograft-tumor growth in vivo." (PMID 30068336, 2018). "Our findings strongly indicate that MASTL regulate β-catenin expression and cellular localization to modulate its transcription activity and c-Myc expression to regulate colon cancer." (PMID 30068336, 2018). "Of note, MASTL knockdown in recurrent tumor cells re-sensitized their response to cancer therapy in vitro and in vivo, and this was similar to our findings in colon cancer cells." (PMID 30068336, 2018). "Overall these data identify MASTL as a novel therapeutic target in limiting colon cancer malignancy and reducing death from the disease." (PMID 30068336, 2018). "We found a similar significant increase in MASTL expression in all stages of colon cancer compared to normal samples, analyzing the TCGA database." (PMID 30068336, 2018). "Mechanistically, we provide strong evidence for a novel role for MASTL in regulating Wnt/β-catenin signaling to modulate c-Myc and Survivin expression in promoting colon cancer." (PMID 30068336, 2018). "We found that immunoblotting using lysates from confluence matched cell lines indeed demonstrated a similar increase in MASTL expression in colon cancer cells versus non- transformed intestinal epithelial cells (IEC-6)." (PMID 30068336, 2018).
colon cancer (continued). "Our data are well aligned with the understanding of the regulatory role for MASTL in cell cycle regulation in colon cancer cells, given that inhibiting MASTL was sufficient to inhibit cell cycle progression and mitosis." (PMID 30068336, 2018). "To corroborate these findings, we further determined MASTL expression in colon tumor samples from a murine model of sporadic colon cancer (CRC; the APCmin mice) and colitis- associated cancer (CAC; AOM/DSS induced mouse model)." (PMID 30068336, 2018). "Mechanistic analysis revealed that MASTL expression facilitates colon cancer progression by promoting the β-catenin/Wnt signaling, the key signaling pathway implicated in colon carcinogenesis, and up-regulating anti-apoptotic proteins, Bcl-xL and Survivin." (PMID 30068336, 2018). "We show that overexpression of MASTL correlates with colon cancer recurrence and progression." (PMID 30068336, 2018). "Overall, our data shed light on the heretofore-undescribed mechanistic role of MASTL in key oncogenic signaling pathway/s to regulate colon cancer progression and chemo-resistance that would tremendously help to overcome drug resistance in colon cancer treatment." (PMID 30068336, 2018). "MASTL overexpression or loss of PP2A-B55 have been associated with increased proliferation, EMT and invasion in several cancer types including breast, lung and colon cancer." (PMID 30555827, 2018). "Interestingly, MASTL was also recently shown to promote Wnt/β-catenin signaling in colon cancer by regulating GSK3β S9 phosphorylation." (PMID 30555827, 2018). "Thus understanding the novel functions of MASTL will help in the development of new colon cancer therapeutic approaches." (PMID 30068336, 2018). "To examine if the observed increase in MASTL mRNA expression was translationally relevant, we determined MASTL expression in a panel of colorectal cancer cell lines, animal models of colon cancer as well as a commercial colon cancer tissue array [immunohistochemical (IHC) analysis; 50 samples]." (PMID 30068336, 2018). "Furthermore, MASTL depleted colon cancer cells demonstrated cell cycle arrest at the G2/M phase and significant increase in apoptosis." (PMID 30068336, 2018). "A significant increase in MASTL expression was observed in tumors from both colon cancer models." (PMID 30068336, 2018). "However, our study builds on these initial findings and not only confirms the causal role of PYCR2 in promoting tumorigenicity and the invasive mobility of colon cancer cells in vitro but also in vivo oncogenic growth by regulating MASTL/Wnt/β-catenin signaling." (PMID 37508547, 2023). "Thus, the inhibition by MASTL of drug-induced cell death may not only account for failure of standard chemotherapy, but may also help explain why MASTL overexpression contributes to the malignant phenotype of colon cancer." (PMID 30068336, 2018).
colorectal cancer (5 papers, 2015 to 2024). A primary or metastatic malignant neoplasm that affects the colon or rectum. "A study found that blocking MASTL expression in colorectal cancer cells led to increased sensitivity to 5FU chemotherapy and reduced expression of SURVIVIN and BCL-XL by activating the Wnt/β-catenin signaling pathway." (PMID 39501138, 2024). "For example, inhibition of MASTL in colorectal cancer cells was reported to induce chemosensitivity to 5FU and down-regulate Survivin and Bcl-xL expression through promoting Wnt/β-catenin signaling." (PMID 32727463, 2020). "Recent studies showed that MASTL is overexpressed in various cancer tissues, including breast, head and neck, and colorectal cancers." (PMID 29976159, 2018). "Mitosis is frequently upregulated in cancer cells and several studies have reported the upregulation of MASTL in various cancer tissues, including breast, head and neck, and colorectal cancers; hence, MASTL inhibition reduces tumor growth in vitro and in vivo." (PMID 29976159, 2018). "Further studies where colorectal cancer (CRC) cells were subjected to 5-fluorouracil (5FU) treatment revealed a sharp increase in MASTL expression upon chemotherapy, along with increases in Bcl-xL and Survivin expression." (PMID 30068336, 2018).
head and neck cancer (5 papers, 2015 to 2020). A primary or metastatic malignant neoplasm affecting the head and neck. "In head and neck cancer, up-regulation of MASTL expression promotes cancer progression and tumor recurrence after initial cancer therapy." (PMID 30068336, 2018). "In head and neck carcinoma MASTL was found involved in progression and recurrence and proposed as therapeutic target." (PMID 26431489, 2015). "Furthermore, increased MASTL expression has been associated with poor outcomes in breast, oral, gastric, colon, and head and neck cancer, suggesting that MASTL plays a master role in carcinogenesis." (PMID 32692487, 2020). "MASTL was reported to regulate the DNA damage response in Xenopus and head and neck cancer cells." (PMID 29976159, 2018). "A similar role of MASTL in tumor resistance has been demonstrated in head and neck cancer patients." (PMID 30068336, 2018).
non-small cell lung carcinoma (4 papers, 2016 to 2020). A group of at least three distinct histological types of lung cancer, including non-small cell squamous cell carcinoma, adenocarcinoma, and large cell carcinoma. "In addition, a genome-wide siRNA screen identified MASTL as a potential target for radiosensitization in non-small cell lung cancer cells." (PMID 29976159, 2018).
breast tumor (3 papers, 2018 to 2023). "None of the proliferation defects caused by MASTL depletion could be rescued by a kinase-deficient mutant, demonstrating the requirement of MASTL catalytic activity for proliferation of breast tumor cells." (PMID 29229993, 2018). "Finally, MASTL protein overexpression in breast tumours was analysed in the Clinical Proteomic Tumour Analysis Consortium (CPTAC) and found to be highly significant for both reduced overall survival and poor progression free survival." (PMID 29743597, 2018). "Collectively, the results obtained in these tumor models suggest that elimination of MASTL activity might be a valuable therapeutic target in specific breast tumors." (PMID 29229993, 2018). "A significant number of breast tumor cell lines were resistant to MASTL depletion despite expressing normal levels of their targets, ENSA and B55, suggesting unknown mechanisms of resistance." (PMID 29229993, 2018). "Moreover, elevated levels of MASTL protein correlate with poor disease outcome, and may have prognostic value in Estrogen Receptor (ER)-positive breast tumors independently of the Ki67 proliferation marker." (PMID 29229993, 2018). "Among them, we demonstrated that MKI-2, the most potent MASTL inhibitor, markedly increases mitotic cell death and induces spindle defects in HeLa and MCF7 cells, and in a 4T1 breast tumor model." (PMID 38129815, 2023).
neuroblastoma (3 papers, 2020 to 2023). Neuroblastoma (NB) is the most common solid, extracranial childhood tumor. "In addition, in silico modeling has shown that MASTL stabilizes Aurora A in neuroblastoma cells." (PMID 38129815, 2023). "Although SC targets tend to have a large number of cycles, the node with the most cycles is rarely a control target, and some control targets are involved in few cycles, such as GWL/MASTL and PP2A in the aurora kinase A neuroblastoma model." (PMID 37072458, 2023).
Thrombocytopenia (3 papers, 2013 to 2018). "One of these gene pairings (MASTL to ANKRD26) is corroborated by the fact that the same two genes are elite disease genes for the same disease (Thrombocytopenia 2) in MalaCards." (PMID 28605766, 2017). "We had previously analyzed a non-syndromic thrombocytopenia candidate gene, MASTL, in this family without finding any causative mutations." (PMID 24069336, 2013).